GPR35 (G protein-coupled receptor 35)
Diseases named in the same sentence as GPR35 in open-access papers (continued):
Sharing a sentence is not in itself a finding about the gene and the disease.
colon carcinoma (14 papers, 2015 to 2025). "GPR35 was found to be implicated in cancer development by numerous studies, especially in colon cancer, but the underlying mechanism is unclear." (PMID 37113762, 2023). "Some studies have reported the upregulation of GPR35 in lung and colon cancer and its association with poor prognosis." (PMID 36614059, 2022). "GPR35 has been also linked to the development of heart, vascular, and colon cancers." (PMID 36210838, 2022). "GPR35 was considered a marker of aggressive tumor cells since it was detected to be expressed at a higher level in a regional lymph node in colon cancer patients." (PMID 37113762, 2023). "The upregulation of GPR35 and its correlation with poor prognoses in lung and colon cancer have been reported." (PMID 36614059, 2022). "The hypermorphic T108M variant of the orphan G protein-coupled receptor GPR35 increases risk for PSC and ulcerative colitis (UC), conditions strongly predisposing for inflammation-associated liver and colon cancer." (PMID 33758004, 2022). "Lastly, Schneditz and colleagues examined the physiological relevance of epithelial GPR35 signaling in spontaneous colon cancer model in mice." (PMID 34790192, 2021). "HT-29 human colon cancer cells are widely used asa cell line expressing GPR35 endogenously.17−19 These expressedhigh levels of mRNA encoding the GPR35b isoform." (PMID 34927014, 2021). "While only a few publications describing the role of GPR35 in cancer have been reported, GPR35 could be a novel target in the modulation of gastrointestinal cancers such as colon cancer." (PMID 37834122, 2023). "Mice lacking GPR35 on their macrophages underwent models of spontaneous colon cancer or colitis-associated cancer." (PMID 33758004, 2022). "A more recent report demonstrated the dual role of GPR35 in promoting colon cancer in that it could directly augment the proliferation of epithelial cells expressing GPR35 and facilitate the formation of a tumor-permissive environment via macrophages." (PMID 36614059, 2022). "Correlations between levels of PRSS3 and PRSS22 mRNAs and CEA, CXCL16, CXCL17, GPR35 V2/3, LGR5, LGR6 and KLK6 mRNA levels in lymph nodes of colon cancer patients." (PMID 40909962, 2025). "Interestingly, GPR35/CXCR8 expression has also been observed in HT-29, a human colon cancer cell line." (PMID 25926795, 2015).
ulcerative colitis (14 papers, 2015 to 2026). An inflammatory bowel disease involving the mucosal surface of the large intestine and rectum. "The majority of primary sclerosing cholangitis patients have concurrent ulcerative colitis, and integrated analysis of GWAS studies for both diseases identified two GPR35 SNPs as having a significant association with primary sclerosing cholangitis." (PMID 25805994, 2015). "The first such report comprised a GWAS for early onset IBD (including Crohn’s disease and ulcerative colitis), which identified a GPR35 SNP associated with ulcerative colitis." (PMID 25805994, 2015). "A genetic alteration in GPR35 (rs3749171, resulting in a T108M change) is associated with primary sclerosing cholangitis (PSC) and ulcerative colitis (UC) risk." (PMID 40736072, 2025). "GPR35 is a poorly understood member of the GPCR super-family that is attracting considerable interest as a therapeutic target in areas ranging from ulcerative colitis to digestive system cancers and neuropathic pain." (PMID 39615676, 2024). "As such, GPR35 has attracted attention as a therapeutic target for the treatment of disorders including hypertension, ulcerative colitis, and asthma." (PMID 29875152, 2018). "A more recent study into ulcerative colitis and primary sclerosing cholangitis, a chronic cholestatic liver disease, has further suggested involvement of GPR35 in IBD." (PMID 25805994, 2015). "Indeed, GPR35 has been proposed as a risk factor for chronic inflammatory disorders of the gut such as IBD and ulcerative colitis." (PMID 25805994, 2015). "The reduction of permeability in colonoids from hGPR35a-HA mice by treatment with lodoxamide suggests that activators of GPR35 might be useful in the treatment of lower gut inflammatory conditions, such as ulcerative colitis, in which mucosal barrier function is compromised." (PMID 39615676, 2024). "The endogenous ligand of GPR35, 5-HIAA, has been recognized to mitigate the symptoms of ulcerative colitis, while the precise role of GPR35 was not delineated further." (PMID 38035084, 2023).
Hypertension (13 papers, 2012 to 2025). The presence of chronic increased pressure in the systemic arterial system. "Furthermore, the receptor for CXCL17, GPR35, has been implicated in pathogenesis of hypertension, coronary artery diseases, and cardiac hypertrophy." (PMID 29925869, 2018). "In this study, researchers found that GPR35 deletion offers protection of EC function during deoxycorticosterone acetate‐salt‐induced hypertension." (PMID 39744893, 2025). "We think that this study provides fresh insights highlighting the therapeutic potential of targeting GPR35 to prevent and treat hypertension." (PMID 34275335, 2021). "Yet, in another study, mice with GPR35 deletion showed resistance to BP elevation in Ang II-induced hypertension." (PMID 34943862, 2021). "GPR35 has a significant role in inflammatory pain, asthma, diabetes, hypertension, cardiovascular disease, and irritable bowel disease." (PMID 34943862, 2021). "In a deoxycorticosterone acetate-salt induced hypertensive model, male GPR35 knockout mice were protected from hypertension with improved endothelium-dependent vasodilation and decreased superoxide in isolated aortas." (PMID 34943862, 2021). "Zaprinast activates the G-protein coupled receptor, GPR35, that plays a crucial role in cardiovascular disease, pain, regulation of inflammation, hypertension, diabetes, and irritable bowel disease." (PMID 32365529, 2020). "To investigate the role of GPR35 in the context of cardiovascular disease, we studied the cardiovascular phenotype of the GPR35 knockout mouse in an Ang II infusion hypertension model." (PMID 29860395, 2018). "GPR35 knockout mice were resistant to the development of Ang II–induced hypertension, suggesting an important role for GPR35 in hypertensive signaling." (PMID 29860395, 2018). "This suggests that GPR35 is a potential novel drug target for therapeutic intervention in hypertension." (PMID 29860395, 2018). "Taken together, the human and mouse studies highlight potential uses for GPR35 as a predictive marker in the development of heart failure and as a target in the treatment of hypertension." (PMID 25805994, 2015). "GPR35 is an orphan GPCR, and has been implicated in hypertension, coronary artery disease, asthma, pain, inflammation, and cancers." (PMID 22511974, 2012). "Research indicates that GPR35 could be a major factor in conditions like inflammatory pain, asthma, diabetes, hypertension, heart disease, and IBD." (PMID 40736072, 2025). "Furthermore, studies on other disease targets, such as the role of the translocator protein (TSPO) in glioblastoma and the potential role of GPR35 in diabetes and hypertension, provide valuable references for understanding the mechanism of action of PF4V1 in NMOSD." (PMID 40294019, 2025). "Although the mechanism by which inactivation of GPR35 attenuates Ang II–induced hypertension remains unclear, this suggests that targeting GPR35 could be a novel target in the therapeutic control of blood pressure, most obviously through the use of GPR35 antagonists." (PMID 29860395, 2018). "Second, although the evidence of GPR35 expressions in human ECs from hypertensive donors would significantly strengthen the study, we could not do so because it was challenging to find human arterial ECs in a population with hypertension as the only disease state." (PMID 34275335, 2021). "The in vivo BP profile of male and female GPR35 knockout mice and their wild-type controls in deoxycorticosterone acetate (DOCA)-salt induced hypertension was acquired." (PMID 34275335, 2021). "Although GPR35 does not appear to influence basal cardiovascular regulation, these findings demonstrate that it plays an important pathological role in the development of Ang II–induced hypertension and impaired cardiac function." (PMID 29860395, 2018).
heart failure (10 papers, 2015 to 2025). Inability of the heart to pump blood at an adequate rate to meet tissue metabolic requirements. "In addition, high amounts of GPR35 were shown to be expressed in the wild-type mice hearts, and myocardial GPR35 gene expression was shown to be associated with human heart failure." (PMID 37616231, 2023). "Indeed, GPR35 was identified among the top 12 genes whose expression correlates with the severity of heart failure and adenoviral overexpression of GPR35 was shown to cause hypertrophic-like morphology changes and reduced cellular viability of cardiomyocytes." (PMID 37616231, 2023). "Also in the context of CVDs, high GPR35 expression in the heart has been associated with heart failure." (PMID 34201526, 2021). "GPR35, a recently deorphanized GPCR, has garnered attention as a potential therapeutic target due to its associations with various pathologies, including heart failure, diabetes and inflammatory diseases." (PMID 39744893, 2025). "GPR35 gene and protein expressions were induced in mouse models of cardiac failure, the acute phase of myocardial infarction, and during the compensatory and decompensatory phase of pressure-load-induced cardiac hypertrophy." (PMID 34943862, 2021). "Second, in a microarray screen of heart failure patients, GPR35 was reported to have increased expression levels in failing myocardium and in vitro overexpression of GPR35 in cardiomyocytes induced hypertrophy and decreased cell viability." (PMID 27064272, 2015). "However, GPR35 serves as an early marker of heart failure because it is upregulated in the myocardial tissues of patients with heart failure." (PMID 38956679, 2024). "Microarray analyses on heart failure patients showed that GPR35 was increased in heart failure." (PMID 34943862, 2021). "GPR35 expression in myocardial tissue from heart failure patients was significantly upregulated compared with that in healthy controls, and GPR35 was among twelve genes selected for follow-up analysis based on its orphan status and its novelty as a potential therapeutic target." (PMID 25805994, 2015). "In the heart, the expression of GPR35 may correlate with heart failure." (PMID 37616231, 2023). "Interestingly, the authors identified GPR35/CXCR8 as a highly expressed in heart failure patients." (PMID 25926795, 2015).
asthma (9 papers, 2012 to 2025). "Wedelolactone, which is antiallergic, was found to be a potent β-arrestin-biased GPR35 agonist and can be considered a potential drug against asthma." (PMID 27355071, 2014). "G protein-coupled receptor-35 (GPR35) has been shown to be a target of the asthma drugs cromolyn disodium and nedocromil sodium." (PMID 27355071, 2014). "Among synthetic compounds, the asthma medications cromolyn disodium and lodoxamide, which serve to stabilize mast cells, have also been shown to be agonists of GPR35, implicating GPR35 in the allergic response." (PMID 29875152, 2018). "Altogether, these results suggest that GPR35/CXCR8 may be an important target in the development of novel asthma and anti-inflammatory medications; for additional review of GPR35/CXCR8 and its relationship to inflammation, see." (PMID 25926795, 2015). "Interestingly, the results of calcium flux and inositol phosphate accumulation assays suggest that the asthma medications cromolyn disodium and nedocromil sodium are agonists of GPR35/CXCR8." (PMID 25926795, 2015). "Additionally, GPR35/CXCR8 has been suggested to be an important target in the treatment of asthma." (PMID 25926795, 2015). "Firstly, the biological activity of the polar ingredient was profiled in related targets according to its clinical indications, including GPR109A (cardiovascular disease), β2-AR (asthma), NTSR (cancer), M3 (asthma) and GPR35 (inflammation)." (PMID 36431815, 2022). "Interestingly, GPR35 mRNA is upregulated upon challenge with IgE antibodies, suggesting that GPR35 may be a potential target for using cromolyn sodium in the treatment of asthma." (PMID 34359931, 2021).
colorectal cancer (8 papers, 2021 to 2026). A primary or metastatic malignant neoplasm that affects the colon or rectum. "Background and purpose: GPR35, a member of the orphan G-protein-coupled receptor, was recently implicated in colorectal cancer (CRC)." (PMID 37113762, 2023). "In the context of IBD and colorectal cancer prevention, this includes nutraceuticals such as kynurenic acid, quercetin, curcumin, and probiotics, which modulate AhR and GPR35 signaling pathways." (PMID 41009721, 2025). "A recent study performed in colorectal cancer (CRC) cells used highly expressed GPR35 and CXCL17 in drug-resistant tumor cells." (PMID 38384293, 2024). "GPR35 is related to colorectal cancer, pancreatic cancer and stomach cancer, while GPR37 is related to glioma, melanoma and liver cancer." (PMID 37743473, 2023). "GPR35 is an emerging GPCR in the intestinal health field with potential implications in IBD as well as colorectal cancer." (PMID 34790192, 2021). "Recently, a constitutive ligand-independent pro-cancer function of GPR35 was reported, demonstrating that GPR35 interacted with Na+/K+-ATPase inducing colorectal cancer (CRC) cell proliferation and glycolysis, also driving macrophages to promote angiogenesis in the tumor microenvironment." (PMID 37113762, 2023).
diabetes (8 papers, 2018 to 2025). "GPR35 has a number of ligands, including kynurenic acid and 2-acyl LPA, and GPR35 has been associated with a number of pathologies, including cardiovascular disease and diabetes." (PMID 31323936, 2019). "GWAS has identified GPR35/CXCR8 SNP that was associated with diabetes." (PMID 34943862, 2021). "However, more studies are required to probe the role of GPR35 in the mediation of glucose homeostasis and diabetes." (PMID 34943862, 2021).
gastric cancer (6 papers, 2022 to 2025). A primary or metastatic malignant neoplasm involving the stomach. "The discharge of enhancers and altered activation of GPR35 leads to the growth and movement of gastric cancer cells, a notable reduction in certain immune cells (CD8 + T cells and CD4 + memory T cells), and/or infiltration (T‐cells and macrophages)." (PMID 40736072, 2025). "According to HR values of GPR35 in different clinical factors for gastric cancer, it further determined that ERR-activated GPR35 plays an important role in the progress of stomach adenocarcinoma development." (PMID 36333291, 2022). "Here, we found that a higher expression of GPR35 in tumors means a poorer prognosis of gastric cancer." (PMID 36333291, 2022). "Therefore, in this study, we focus on the function of GPR35 in gastric cancer and their tumor microenvironment." (PMID 36333291, 2022). "We also proved that orphan GPR35 is potentially activated by ERR events in gastric cancer." (PMID 36333291, 2022). "Hence, GPR35 potentially acts as a biomarker for monitoring and early warning of primary gastric cancer." (PMID 36333291, 2022). "GPR35 remains poorly characterized and has been slow to amass interest in gastric cancer therapy." (PMID 36333291, 2022). "However, GPR35 was found it was also highly expressed in stomach tissues and related to the development and immune infiltration for gastric cancer tumors in this study." (PMID 36333291, 2022). "Furthermore, compared to kidney cancer (Pan-kidney cohort, KIPAN), ERR event in gastric cancer resulted in a higher ratio between GPR35 and CAPN10." (PMID 36333291, 2022). "Hence, GPR35 could act as a genetic indicator of primary stomach cancer and a good drug target for almost all clinical types of GC patients." (PMID 36333291, 2022). "To explore the molecular features of macrophage which is affected by GPR35, we downloaded single-cell RNA sequencing data in gastric antral mucosa biopsies of patients spanning a cascade of gastric premalignant lesions and early gastric cancer (EGC) from the NCBI GEO database (GSE134520)." (PMID 36333291, 2022). "In gastric cancer, enhancer release and relocalization (ERR) activates GPR35 expression in tumor tissues, promoting disease progression and negatively impacting patient prognosis." (PMID 41459506, 2025). "Gastric cancer cells have been shown to have a higher expression of GPR35 mRNA than noncancerous gastric mucosa, while non-small-cell lung cancer tissue had an overexpression of GPR35 relative to normal lung tissue resulting in drug resistance." (PMID 37834122, 2023). "Hence, our systematic study of ERR events in GPR35 and its biological functions in gastric cancer will serve as a valuable resource for exploring a novel activation pathway for oGPCRs and finding early genetic indicator and druggable receptor for GC patients." (PMID 36333291, 2022). "Hence, we compared GPR35 and CAPN10 expression fluctuation in kidney and gastric cancer tissues, but also their relationship in kidney cell and gastric cancer cells when knocked out CTCF-bd (binding domain) for CAPN10." (PMID 36333291, 2022). "However, many researches focus on GPR35 functions in the intestine, not stomach cancer recently." (PMID 36333291, 2022).
Obesity (6 papers, 2021 to 2025). Accumulation of substantial excess body fat. "In general, GPR35-mediated signaling has been implicated in promoting anti-inflammatory responses and to prevent disease, including colitis, mast cell-mediated allergic reactions, and adipose tissue inflammation in obesity." (PMID 34201526, 2021). "Activation of GPR35 has been shown to reduce weight gain and fat accumulation in metabolic disorders such as obesity and type 2 diabetes, suggesting its relevance to lipid metabolism." (PMID 41415839, 2025). "G protein-coupled receptor 35 (GPR35), an orphan receptor highly expressed in gut epithelial and myeloid cells, has been shown to mitigate obesity-related MASH through the regulation of hepatic cholesterol homeostasis." (PMID 40351307, 2025). "One such metabolite, kynurenic acid (KYNA), promotes thermogenesis in adipose tissue and suppresses HFD-induced obesity by activating G-protein coupled receptor 35 (GPR35)." (PMID 41488302, 2025). "In human adipose tissue, GPR35 expression correlates with genes involved in transcriptional regulation of adipocyte browning, an event that can be explored as a therapeutic target for obesity." (PMID 37895892, 2023). "Nevertheless, considering that atherogenesis is influenced by several risk factors, including comorbidities like obesity and other auto-immune diseases that have been associated with GPR35, our study does not completely rule out its potential relevance for CVDs." (PMID 34201526, 2021). "For obesity‐induced T2DM, several class A orphan GPCRs, including GPR21, GPR35, GPR84, and GPR132, are suggested to play an active role in the developmental processes of T2DM." (PMID 36721851, 2023).
primary sclerosing cholangitis (6 papers, 2015 to 2025). "Deficiency of GPR35 has been associated with IBD, both UC and Crohn’s disease, as well as primary sclerosing cholangitis." (PMID 38667792, 2024).